NINJ1 (ninjurin 1)
Diseases named in the same sentence as NINJ1 in open-access papers (continued):
Sharing a sentence is not in itself a finding about the gene and the disease.
bacterial infection (3 papers, 2021 to 2024). "NINJ1 deficiency increases susceptibility to bacterial infection, presumably by limiting critical inflammatory responses initiated by DAMPs." (PMID 36695550, 2023). "Recently, NINJ1 was shown to be important for inflammatory responses in bacterial infection and several liver injury models in mice, possibly by controlling PMR and the release of DAMPs3,4,25,26." (PMID 39483869, 2024). "Our data extend recent findings describing NINJ1 as a regulator of cell lysis downstream of caspase activation and gasdermin cleavage, and highlight the role of lytic cell death in host defense against bacterial infection." (PMID 34648590, 2021). "Altogether these data indicated that NINJ1-mediated cell lysis is not important for control of cell-intrinsic cytokine production but contributes to host defense against bacterial infection." (PMID 34648590, 2021).
cardiovascular diseases (3 papers, 2025 to 2026). "In recent years, Ninj1, an important protein associated with inflammasome activation, has garnered increasing attention from researchers regarding its mechanistic role and pathophysiological significance in cardiovascular diseases." (PMID 42004242, 2026).
neurological diseases (3 papers, 2017 to 2026). "In this cohort, seven genes have already been associated with neurological disorders (MNX1, NINJ1, PER2, PHF20, PRSS56, RPH3A, and SBF1) in MalaCards and OMIM." (PMID 28769055, 2017). "Finally, we evaluate therapeutic strategies targeting NINJ1 (including monoclonal antibodies, functional peptides, and small-molecule inhibitors) and their potential applications in neurological diseases." (PMID 42292377, 2026). "In conclusion, NINJ1 can fulfill its role in the nervous system by mediating the repair and regeneration of nerves and blood vessels as well as neuroinflammation, suggesting its potential as a potent therapeutic target for neurological diseases." (PMID 39958360, 2025).
bone disorder (1 paper, 2019). "To investigate the potential association between NINJ1 expression and bone disorders in humans, we mined publicly available data sets in GEO and analyzed four different microarrays." (PMID 30700695, 2019). "Together, these data suggest that NINJ1 has a potent role in human bone disorder pathogenesis and/or progression." (PMID 30700695, 2019). "Finally, analysis of publicly available microarray data sets revealed a potent correlation between high NINJ1 expression and destructive bone disorders in humans." (PMID 30700695, 2019). "Our findings suggest that Ninj1 has a novel role in OC development and bone homeostasis and might represent a potent therapeutic target for destructive bone disorders." (PMID 30700695, 2019).
NINJ1 also shares sentences with these, for which no sentence is quoted: acute kidney injury (2 papers); idiopathic pulmonary fibrosis (2); Yersinia infection (2); acute lung injury (1); acute respiratory distress syndrome (1); aortic aneurysm (1); aortic stenosis (1); Arterial thrombosis (1); brain injury (1); cerebral infarction (1); chronic myeloid leukemia (1); Cirrhosis (1); CNS disorders (1); dissection (1); Disseminated intravascular coagulation (1); erectile dysfunction (1); fibrosarcoma (1); fibrosis (1); Fulminant hepatitis (1); gout (1); head–neck squamous cell carcinoma (1); heart failure (1); influenza (1); Kawasaki disease (1); kidney damage (1); liver cancer (1); lung adenocarcinoma (1); metabolic disease (1); metastatic melanoma (1); myocardial infarction (1).
A further 7 diseases each share a sentence with NINJ1 in 1 paper.